IL6 (interleukin 6)
Diseases named in the same sentence as IL6 in open-access papers (continued):
Sharing a sentence is not in itself a finding about the gene and the disease.
periodontitis (continued). "IL-6 is one of the key cytokines involved in the development of periodontal disease, with elevated levels reported in the blood and gingival fluid of patients with periodontitis." (PMID 41154857, 2025). "In this study, we found that periodontitis and periodontitis-associated metabolite Ile enhanced NF-κB signaling in IECs to impair epithelial barrier function and increase the expression of pro-inflammatory cytokines (TNF-α, IL-6, and IL-1β)." (PMID 41394102, 2025). "The proposed explanation for this association is based on the idea that periodontitis could influence inflammatory biomarkers, such as TNF-α, Interleukin 1 Beta (IL-1β), and Interleukin 6 (IL-6), which may contribute to increased blood pressure." (PMID 40002786, 2025). "Additionally, other interleukin family members, such as interleukin-6 (IL-6)-related pathways, have been reported to be closely associated with inflammation responses in IBD and periodontitis." (PMID 40002889, 2025). "A prospective cohort study demonstrated that individuals with high levels of both IL-6 and CRP, along with moderate-to-severe periodontitis and type 2 diabetes, had a 2.3-fold increased risk of major adverse cardiovascular events compared to individuals with none of these risk factors." (PMID 41007869, 2025). "The pathogenesis of periodontitis is primarily driven by dysbiotic microbial communities that initiate an inflammatory cascade involving the upregulation of cytokines such as interleukin-6 (IL-6), tumor necrosis factor-alpha (TNF-α), and nuclear factor kappa B (NF-κB)." (PMID 41150759, 2025). "However, to date, no study has evaluated irisin's probable role in the development of plaque-induced gingivitis patients or the pathogenesis of irisin together with visfatin and IL-6 in periodontitis." (PMID 41280712, 2025). "Local inflammatory responses in periodontitis are characterized by the release of cytokines (IL-1β, IL-6, TNF- α), prostaglandins, and matrix metalloproteinases (MMPs) from resident and infiltrating immune cells, leading to tissue destruction and alveolar bone resorption." (PMID 40941475, 2025). "In addition, elevated levels of inflammatory biomarkers such as IL-6 and CRP in mothers with periodontitis are linked to impaired placental function." (PMID 40703374, 2025). "Chronic infections, including periodontitis, might increase circulating cytokines and factors, such as C-reactive protein, interleukin-1 beta, interleukin-6, tumor necrosis factor-alpha, and prostaglandin-E2." (PMID 39229981, 2025). "Furthermore, the coexistence of periodontitis and cancer seems to potentiate IL-6 production, potentially leading to increased regulatory T-cell infiltration and promoting tumor progression." (PMID 40944094, 2025). "The pathways, such as IL-17 signaling and cytokine–cytokine receptor interactions, underline the important role of proinflammatory cytokines like IL-17, TNF-α, and IL-6 in driving neutrophil recruitment and amplifying the inflammatory response during periodontitis." (PMID 40076622, 2025). "IL-6 is a pro-inflammatory cytokine involved in the pathogenesis of periodontitis." (PMID 40282186, 2025). "The significant correlation between cortisol and IL-6 and IL-1β also suggests that specific inflammatory pathways may mediate the stress–periodontitis axis." (PMID 40843742, 2025). "Preeclampsia, initiated by periodontitis, results in elevated IL-6 and CRP in early pregnancy." (PMID 41394354, 2025). "Notably, patients with moderate chronic periodontitis have been shown to exhibit higher serum IL-6 levels compared to healthy individuals or those with mild disease." (PMID 41586318, 2025). "Among them, cytokines such as TNF-α, IL-1β, and IL-6 are highly expressed in patients with periodontitis and promote bone resorption by directly or indirectly supporting not only inflammation but also soft tissue degradation, lymphocyte promotion, and osteoclast formation." (PMID 40733170, 2025).
periodontitis (continued). "Periodontal tissues of patients with periodontitis show increased production of inflammatory cytokines and elevated levels of inflammatory markers such as C-reactive protein, tumor necrosis factor-alpha, and interleukin-6 in the blood." (PMID 40076415, 2025). "We hypothesize that patients with more severe forms of periodontitis would exhibit higher salivary cortisol, as well as elevated levels of IL-1β and IL-6, reflecting a coordinated neuroendocrine inflammatory response associated with disease progression." (PMID 40843742, 2025). "The study compared stage III periodontitis patients with healthy controls, analyzing saliva and serum for Kyn pathway metabolites, including Trp, Kyn, kynurenic acid (KynA), picolinic acid (PA), QA, and interleukin-6 (IL-6)." (PMID 41002365, 2025). "During periodontitis, IL-6 and IL-1β have an opposite role in connective tissue turnover." (PMID 40182222, 2025). "Indeed, patients with periodontitis display increased levels of IL-6 and TNF-α in serum, saliva and gingival crevicular fluid." (PMID 39274511, 2024). "Similarly, “inflammatory depression” induces a functional alteration of the HPA axis with increased secretion of pro-inflammatory cytokines such as IL-6 and TNF-α; the latter are in turn associated with the development of periodontitis." (PMID 39124790, 2024). "While elevated salivary IL-6 levels may indicate local inflammation in periodontitis, elevated IL-1β levels suggest its participation in thyroid pathophysiology and as a potential marker for the disease." (PMID 39063437, 2024). "A 2010 study showed that the IL-6-174 G/G genotype was associated with periodontitis in non-smokers and older subjects (>45 years old) in an Indian population." (PMID 38396821, 2024). "The transition from predominantly aerobic and Gram-positive bacteria in healthy gingiva to gram-negative bacteria, particularly the “red complex” pathogens in periodontitis, promotes the release of pro-inflammatory cytokines such as interleukin-1β (IL-1β), IL-6, and TNF-α." (PMID 39768299, 2024). "Furthermore, previous studies have shown that PL effectively downregulates IL-1β expression in a mouse model of osteoarthritis, as well as inhibits TNF-α and IL-6 levels in a rat model of chronic periodontitis, which aligns with our observations." (PMID 38655086, 2024). "Meanwhile, in rats with glucocorticoid-induced osteoporosis submitted to periodontitis, ATV at 27 mg/kg decreased bone loss, reduced myeloperoxidase (MPO), TNF-α, IL-1β, IL-6, and IL-8, and increased IL-10, glutathione (GSH), superoxide dismutase (SOD), and catalase (CAT) levels." (PMID 39476053, 2024). "Additionally, inflammatory markers such as IL-1b, IL-6 and TNF-α are associated with periodontitis and HIV, and possibly elicit HIV reactivation." (PMID 38885222, 2024). "Moreover, we also observed that pro-inflammatory cytokines TNF-α and IL-6 had higher gene expression in the periodontitis group." (PMID 38319542, 2024). "Pathogens linked to periodontitis, such as Porphyromonas, Fusobacterium, and Treponema, are more abundant in the subgingival plaques of HTN participants and are positively correlated with IL-6 and/or CRP levels." (PMID 39203574, 2024). "Nevertheless, systematic reviews and meta-analyses have identified significant associations between genetic variants in genes like interleukin 1A (IL-1A), interleukin 1B (IL-1B), IL6, IL10, the matrix metalloprotease 3 (MMP-3), and matrix metalloprotease 9 (MMP-9) and periodontitis risk." (PMID 39337647, 2024). "Therefore, we evaluated the effect of HKT on pro-inflammatory mediators iNOS and COX-2 and the major inflammatory cytokines of periodontitis, IL-6, IL-1β, and TNF-α, in an actual inflammatory situation." (PMID 38790655, 2024). "IL-6–dependent Th17-to-Tfh plasticity during periodontitis limits disease pathology." (PMID 38819409, 2024).
periodontitis (continued). "Additionally we examined the expression of IL-6 in gingival tissue in patients with periodontitis and control subjects, as well as the correlation between gingival expression of IL-6 and clinical parameters." (PMID 39458264, 2024). "Particularly high IL-6 levels were observed in elder patients with periodontitis." (PMID 39253090, 2024). "Additionally, clinical trials have demonstrated that individuals with periodontitis exhibit significantly elevated concentrations of IL-6, a critical signaling molecule that facilitates Th17 differentiation, compared with the control group." (PMID 39215253, 2024). "Macrophages play a key role in both the destructive and reparative phases of periodontal disease, as they differentiate into M1-type during the early stages of periodontitis and secrete high levels of pro-inflammatory cytokines such as IL-1β, IL-6, TNF-α, and IFN-γ." (PMID 38319542, 2024). "Moreover, M1-related cytokines, including as MMP-9, IL-6, and IFN-γ, have been demonstrated to aggravate periodontitis by promoting alveolar bone loss." (PMID 38907216, 2024). "No doubt, tissue affected by periodontitis is associated with an imbalance between pro and anti-inflammatory cytokines (IL-17, IL-23, IL-6, IL-8, TNF-α, and interferon-γ) in favor of pro-inflammatory burden." (PMID 39445112, 2024). "P. gingivalis may affect the progression of BPH through IL-6/IL-6R inflammation and Akt signaling pathways, suggesting that the distal metastasis of oral pathogens is a possible mechanism for periodontitis to promote BPH." (PMID 38764065, 2024). "Consequently, IL-6 is involved in inflammatory immune diseases such as Crohn’s disease, systemic lupus erythematosus, and also periodontitis." (PMID 39629237, 2024). "In the group of patients with periodontitis, we did not demonstrate an association of gingival IL-6 expression with clinical parameters." (PMID 39458264, 2024). "Furthermore, it was demonstrated that the more severe periodontitis is, the greater the magnitude of the positive association between ACE2 and IL-6." (PMID 39917640, 2024). "We found that the severe periodontitis group presented a statistically significantly lower frequency of IL-6-producing monocytes and IL-6 expression by these cells (after stimulus) (p = 0.001 and p = 0.10, respectively) compared to the moderate periodontitis group." (PMID 39274511, 2024). "The proinflammatory signaling cascade triggered in periodontitis causes hyperpermeability of endothelial cells and the subsequent release of cytokines/interleukins (TNF-α, IL-1, IL-6) into the bloodstream, which affect endothelial function, causing alterations in the vascular structure." (PMID 38396672, 2024). "Importantly, IL-6 and MMP-8 results validated the biological separation of groups associated with the clinical progression of periodontitis, supporting proteomic findings and offering additional protein-level evidence." (PMID 38802345, 2024). "Another systematic review with meta‐analysis showed that in patients with heart and kidney transplants, there was evidence that periodontitis is associated with higher serum levels of IL‐6 than those without periodontitis." (PMID 39494478, 2024). "Additionally, a clinical study found that periodontitis therapy significantly reduced levels of inflammatory factors IL-6, IL-8, and CRP in patients with atherosclerotic cardiovascular disease with high CRP levels (CRP ≥ 3 mg/L)." (PMID 39203574, 2024). "IL-6 detected in the GCF of periodontitis patients enhances the synthesis of collagen." (PMID 38420070, 2024). "IL-6 may indirectly contribute to bone resorption in periodontitis through interaction with IL-6 receptors on osteoblastic cells." (PMID 38670955, 2024). "Further, IL-6 is involved in the pathogenesis of periodontitis." (PMID 38627806, 2024).
periodontitis (continued). "Periodontitis, as a chronic inflammatory disease, triggers the release of pro-inflammatory cytokines such as interleukin-6 (IL-6), interleukin-1β (IL-1β), and tumor necrosis factor-alpha (TNF-α), which not only mediate tissue destruction in the periodontal tissues but also activate the SNS." (PMID 39590320, 2024). "Using real-time PCR, the association between the SARS-CoV-2 receptor angiotensin-converting enzyme 2 (ACE2) and miRNA-200c-3p and miRNA-421-5p as well as interleukin-6 (IL-6) was examined in the saliva of moderate (G1, n = 10) and severe (G2, n = 10) periodontitis subjects." (PMID 39917640, 2024). "Notably, ErL as adjunct therapy was revealed to reduce IL-6 expression in gingival crevicular fluid (GCF) in patients with chronic periodontitis compared to scaling and root planing (SRP) alone." (PMID 38396793, 2024). "IL6 and CXCL8/IL8 are central cytokines in the inflammatory response, and their dysregulation has been strongly implicated in the pathogenesis of periodontal diseases such as gingivitis and periodontitis." (PMID 39769290, 2024). "In conclusion, genetically proxied downregulation of IL-6 signaling was associated with lower odds of periodontitis and CRP might be a causal target for the effect of IL-6 on the risk of periodontitis." (PMID 37342352, 2023). "The structure of the IL1β protein and its interaction with the RNA around the alternate or reference SNPs at IL6-1363 might provide information as to how this form of epistasis operates in periodontitis; Supplement, Section S4." (PMID 37762554, 2023). "Polymorphisms were not affected by the severity of chronic periodontitis, IL-6 levels, and CRP levels." (PMID 37239434, 2023). "Antihypertensive blockers of Ang II receptors have been effective in inhibiting the production of IL-6, TNF-α, and receptor activator of the nuclear factor kappa-Β ligand, and consequently, they reduce alveolar bone loss in rats with experimental periodontitis." (PMID 37568542, 2023). "Similarly, the hepatic expression of proinflammatory cytokines IL-6 and IL-1b observed in MetS and periodontitis are further enhanced when both processes occur simultaneously." (PMID 37176029, 2023). "Another study showed the presence of CRP and IL-6 in periodontitis patients with CAD." (PMID 37239434, 2023). "A potential link between periodontitis/gingivitis and graft rejection could be a periodontitis-related, IL-6-modulated, pro-inflammatory state." (PMID 37767526, 2023). "Therefore, we investigated the roles of IL-6 -572 C/G, CRP -757 A/G, and CRP -717 T/C gene polymorphisms; IL-6 levels; and CRP levels on the occurrence of chronic periodontitis related to CAD patients." (PMID 37239434, 2023). "In addition, inflammatory factors of periodontitis, such as IL-1β, IL-6, IL-8, and TNF-α also significantly reduced in the Fn+AKK group." (PMID 37460552, 2023). "However, treatment with FK506/EPO effectively suppressed the increase in serum TNF-α, IL-1β, and IL-6 induced by experimental periodontitis." (PMID 38239915, 2023). "Additionally, P. gingivalis promotes pathogenesis of aggressive periodontitis by inducing the production of proinflammatory cytokines, such as IL-1β and IL-6, from peripheral T helper cells." (PMID 38149100, 2023). "Additionally, it has been documented that periodontitis increases systemic inflammation markers, such as interleukin-6 (IL-6) and C-reactive protein (CRP)." (PMID 37568161, 2023). "Expression levels of IL1β, IL6, IL17α, and TNF-sf11 were significantly lower in P2×r5−/− mice compared to WT mice, and this reduction led to decreased periodontitis (gum disease) and decreased alveolar bone loss compared with WT mice, when challenged by LPS from Porphyromonas gingivalis." (PMID 36279087, 2023). "Similarly, in our study, we find that NAC‐S2 treatment significantly suppresses the mRNA expression levels of TNF, IL6, and IL‐1β in gingival tissues of periodontitis mice, indicating the protecting role of NAC‐S2 in periodontitis." (PMID 37647428, 2023).
periodontitis (continued). "Beyond that, the involvement of IL-6 in the development of periodontitis is well recognized." (PMID 37342352, 2023). "Additionally, significant differences in TNFα and IL-6 levels were found between patients in accord with the mild, moderate, and severe periodontitis stages." (PMID 36599866, 2023). "Periodontitis pathogens can stimulate cells to produce inflammatory factors such as IL-1β, IL-6, and TNF-α and enter the body circulation system through the broken gingival epithelium in periodontal pockets, causing bacteremia, or ectopic colonization in other organs." (PMID 37808891, 2023). "Whether periodontitis and carious lesions in teeth contributed to elevated IL-6 level need to be discussed." (PMID 37608339, 2023). "The presence of inflammatory mediators in periodontitis, such as IL-1, IL-1 β, IL-4, IL-6, IL-8, IL-10, TNF and IFN-γ, together with macrophages sensitized by M. leprae in the bloodstream can exacerbate the host’s immune response, triggering the leprosy reaction." (PMID 37418096, 2023). "Based on the previous study, the IL-6 -572 C ⁄G gene polymorphism did not correlate with chronic periodontitis susceptibility, but it was significantly different between the CAD and non-CAD groups." (PMID 37239434, 2023). "Interestingly, IL-6 levels affected CRP levels in periodontitis patients with CAD (path coefficient 0.322, p = 0.003)." (PMID 37239434, 2023). "However, in the present study, the IL-6 and IL-17A production during the 2 years of orthodontic treatment was lower than those detected during previous periodontitis." (PMID 36902236, 2023). "Some of them, such as IL-1β and IL-6, in saliva could be candidates for early diagnosis of periodontitis." (PMID 36983201, 2023). "Patients with periodontitis had considerably higher levels of IL-6 in their saliva and serum." (PMID 36769328, 2023). "Higher systemic circulating inflammatory burden of CVD risks such as interleukin (IL)-1β, IL-8, IL-6 and tumor necrosis factor-alpha (TNF-α) are directly associated with the periodontitis incipient lesions in adolescents and established periodontitis in adults." (PMID 37711554, 2023). "Further genetic studies could help dissect the downstream effect of IL-6 signaling on periodontitis." (PMID 37342352, 2023). "Our results showed that the presence of SB significantly inhibited inflammatory cell infiltration and prevented the increase of the relative mRNA expression of TNF-α, IL-1β, and IL-6 in both in vivo and in vitro models, which indicates that SB effectively inhibited the inflammation in periodontitis." (PMID 36846719, 2023). "In periodontitis, the expression of inflammatory cytokines, such as interleukin-1 beta (IL-1β), interleukin-6 (IL-6), and tumor necrosis factor-alpha (TNF-a), is increased, and it is closely related to the destruction of periodontal tissue and alveolar bone loss." (PMID 37240020, 2023). "Periodontitis is a common chronic inflammatory disease that is characterized by disordered glucose metabolism and the cytokines: interleukin-1 (IL-1), interleukin-6 (IL-6), tumor necrosis factor-α (TNF-α), and interleukin-17A (IL-17A)." (PMID 38098816, 2023). "In individuals with systemically healthy periodontitis, it is unclear whether successful periodontal treatment significantly decreases the circulating levels of inflammatory markers like IL-6 or TNF-α." (PMID 38132485, 2023). "Periodontitis is one of the diabetic complications that induces the production of inflammatory cytokines such as interleukin-1 (IL-1), interleukin-6 (IL-6), interleukin-8 (IL-8), interleukin-17 (IL-17), and tumor necrosis factor-α (TNFα) and reduced anti-inflammatory cytokines under hyperglycemia." (PMID 37408216, 2023). "The rationale behind those hypotheses was that patients with periodontitis exhibit higher systemic levels of inflammatory mediators such as interleukin (IL-2, IL-6) and tumor necrosis factor (TNF-α)." (PMID 37735212, 2023).